MIR516B1 (microRNA 516b-1)
Synonyms: hsa-mir-516-4; hsa-mir-516b-1; MIRN516-4; MIRN516B-1; MIRN516B1; mir-516b-1
Gene: MicroRNA gene on chromosome 19 (53,736,845 to 53,736,934, forward strand). Ensembl gene ENSG00000207946.
Gene Ontology:
Biological process: miRNA-mediated post-transcriptional gene silencing
Homologues: Orthologues: macaque mml-mir-516b (100% identical), chimpanzee ptr-mir-516b-1 (99% identical). Paralogues in human: MIR516A1 (92% identical), MIR516A2 (91% identical), MIR520C (86% identical), MIR518E (84% identical), MIR526A1 (84% identical), MIR518F (83% identical), MIR519A2 (83% identical), MIR519C (83% identical), MIR522 (83% identical), MIR523 (83% identical), MIR518C (82% identical), MIR520E (82% identical), and 12 more.